CYP2C19 (cytochrome P450 family 2 subfamily C member 19)
Diseases named in the same sentence as CYP2C19 in open-access papers (continued):
Sharing a sentence is not in itself a finding about the gene and the disease.
cancer (continued). "Moreover, CYP2C9 is reportedly associated with the risk of colorectal cancer 16, while CYP2C18 was found to have no contribution to cancer risk 11 and CYP2C19 has been associated with peptic ulcer disease 17, colorectal adenoma recurrence 18, breast cancer 19, and cardiovascular diseases." (PMID 29479826, 2018). "In chemical carcinogenesis metabolism, benzo[a]pyrene can be metabolized by CYP2C8, CYP2C9, CYP2C18, and CYP2C19, and then finally transformed into the DNA adduct (+)‐trans‐BPDE‐N2‐dG, which has been shown to promote cancers of the skin, lung, and stomach." (PMID 29479826, 2018). "But, it should be noted that the levels (pg ml−1) of the cytokines observed in cancer patients in this study is approximately 100-fold lower than the 10 ng ml−1 concentrations of IL-6 and TGF-β required to significantly downregulate CYP2C19 mRNA in vitro." (PMID 18854824, 2008). "Concerning CYP2C19, studies showed that CYP2C19 activity was not solely predicted by the genotype in cancer patients." (PMID 34867341, 2021). "Included patients received the same anticancer therapy and did not take CYP2C19 inhibitors, indicating conversion of CYP2C19 NM to CYP2C19 PM due to the cancer disease state." (PMID 32906709, 2020). "In this field, numerous studies conducted on different populations and ethnic groups have indicated the absence of a major impact of the CYP2D6, CYP2C19 and CYP2E1 genes in cancer risk." (PMID 18423013, 2008). "Likewise, the population PK investigation of the recently approved anti-cancer drug belzutifan revealed that the dual UGT2B17 and CYP2C19 poor metabolizers are expected to show a 3.2-fold AUC, which could lead to adverse events." (PMID 39204377, 2024). "In summary, the IHC data from tumors and lungs suggest that the expression of FABP4, FABP5, or CYP2C19 is not solely come from cancer cells but also from resident or infiltrating stromal cells in tumor and lung microenvironments, affecting TNBC tumor growth or metastasis." (PMID 31941087, 2020). "Thus currently, the mediators of the decreased activity of CYP2C19 in advanced cancer are not apparent." (PMID 18854824, 2008). "The aim of this study was to confirm whether or not CYP2C19 activity is decreased in patients with advanced cancer and to determine whether a relationship exists between CYP2C19 metaboliser status and inflammatory markers such as cytokines and acute phase response proteins." (PMID 18854824, 2008). "Hence, the inflammatory mediators in this population of advanced cancer patients may not have achieved levels high enough to have an effect on CYP2C19 activity." (PMID 18854824, 2008). "However, no patients in this study had taken any medications that could induce or inhibit CYP2C19 and patients had not received any cancer chemotherapy for at least 4 weeks before the study." (PMID 18854824, 2008). "However, in this study in advanced cancer patients, we could not find evidence of a relationship between CYP2C19 activity and serum levels of cytokines or the acute phase response protein CRP." (PMID 18854824, 2008). "We first compared the total EET concentrations in CYP2C19 knockdown cells, or cells treated with 500 nM 17-ODYA (a CYP450 enzyme inhibitor known to lower EET levels in several cancer cell lines), 500 nM HET0016 (a non-specific CYP inhibitor), and 500 nM AUDA (a specific sEH inhibitor)." (PMID 31072371, 2019).
tumor (19 papers, 2014 to 2025). "In the TCGA database, low expression of CYP2C8, CYP2C9, and CYP2C19 in tumor tissue was associated with short median survival." (PMID 36557005, 2022). "To verify the results of the GEP analysis, we evaluated the association between the expression of the CYP2C19 gene in the microarray analysis and those in RT-PCR of the tumor tissue using Spearman’s correlation coefficient." (PMID 29774122, 2018). "Genetic variants of CYP2C19 DNA are polymorphic and the common CYP2C19*2 and CYP2C19*3 alleles have nucleotide mutations that cause a splicing error and generation of a termination codon, which result in enzyme deficiency in non-tumor tissue of the liver." (PMID 29774122, 2018). "In TCGA database, low expression of CYP2C8,CYP2C9, and CYP2C19 in tumor tissue was associated with a short median survival time (all crude P = 0.001, adjusted P = 0.004, P = 0.047, and P = 0.020, respectively)." (PMID 29479826, 2018). "The combination in donor of GG variant in ABCC2 rs2273697 with AG or AA variants in rs4244285 of CYP2C19 metabolizer gene could reduce the risk of tumor occurrence, with an OR < 0.2 in both cases." (PMID 40761554, 2025). "Also, the downregulation of the CYP2C19 gene is associated with aggressive tumor potential and poorer recurrence-free survival of HCC." (PMID 34423049, 2021). "Indeed, the hepatic expression of CYP2C19 could for example be regulated by other tumor-associated inflammatory factors than those regulating CYP3A." (PMID 34867341, 2021). "CYP2C19 influences metabolism (particularly the detoxification of carcinogens) as a tumor suppressor." (PMID 36557005, 2022). "Among the 7 conditions, the expression levels of cyp1a2 and cyp2c19 in the non-tumor tissues were greater than those in the HCC tissues." (PMID 33757544, 2021). "Does the increased YY1 in tumours associate with heightened levels of CYP1B1, mGluR5, P2Y1, O-demethylation and CYP2C19, and thereby with the “backward” conversion of melatonin to NAS and TrkB-driven GSC, survival and proliferation?" (PMID 35582450, 2020). "We then examined the levels of Ki67, FABP4, FABP5, and CYP2C19 in tumor and lung tissues by IHC staining." (PMID 31941087, 2020). "The staining for CYP2C19 protein was classified according to the percentage of positive cells: staining in ≥ 5% of tumor cells was regarded as positive and in < 5% of cells as negative." (PMID 29774122, 2018). "Altogether, these results indicate that the tumor characteristics of CYP2C19 deletion carriers are related to estrogen responsiveness." (PMID 25466287, 2014). "After CPG/PPa NPs entering into tumor cell, CPG responded to CYP2C19 to form metabolites containing mercapto alcohols and destroy the redox homeostasis of tumor cells by consuming GSH, showed synergistic anti-tumor effect, and then enhance the efficacy of PDT in the 4T1 breast tumor xenograft model." (PMID 34796163, 2021). "We have shown, using fresh tumor specimens that EETs and CYP2C19 were upregulated in TNBC tumors, which correspond to the co-upregulation of fatty acid binding proteins, adipocyte signaling, and metastasis-related processes deciphered using pathway deregulation analysis." (PMID 31941087, 2020). "Notably, the CYP2C19 level in tumor cells exerts crucial influence on the synergistic antitumor effect of CPG/PPa NPs, due to its important role in the activation of CPG." (PMID 32373230, 2020). "We hypothesized that FABP4 and FABP5 are critical nodes for EET-driven TNBC oncogenic signaling because these lipid chaperone proteins are upregulated in metastatic TNBC tumor specimens overexpressing CYP epoxygenases (CYP2C19)." (PMID 31941087, 2020). "In the IHC analysis, CYP2C19 protein was stained in the cytoplasm of non-tumor cells." (PMID 29774122, 2018). "All currently identified mutation positive individuals were heterozygous for the CYP2C19 deletion, and the genotype of the remaining allele seemed not to play a role in the observed association with tumor triple-negativity." (PMID 25466287, 2014).
tumor (continued). "The genes found to be down-regulated in tumor tissue were CYP3A4 in 56 patients (61%), CYP2C8 in 44 patients (48%), CYP2C19 in 30 patients (33%), CYP2D6 in 11 patients (12%), CYP3A5 in 7 patients (8%) and CYP1B1 in 2 patients (2%)." (PMID 29774122, 2018). "Looking closely at the SCC-820 genes that were frequently up-regulated or down-regulated in tumor tissue, especially those that were down-regulated—in addition to CYP3A4—both CYP2C8 and CYP2C19 were included in the top thirty genes." (PMID 29774122, 2018). "The GEP analysis showed that the down-regulated genes in tumor tissue were CYP3A4 in 56 patients (61%), CYP2C8 in 44 patients (48%), CYP2C19 in 30 patients (33%), CYP2D6 in 11 patients (12%), CYP3A5 in 7 patients (8%) and CYP1B1 in 2 patients (2%)." (PMID 29774122, 2018). "The tumor size in the patients with down-regulation of the CYP2C19 gene was significantly greater than in those without down-regulation of the CYP2C19 gene (P = 0.005)." (PMID 29774122, 2018). "Tumor size negatively correlated with CYP2C8 and CYP2C19 levels." (PMID 25526449, 2014).
cardiovascular disease (18 papers, 2011 to 2026). "The polymorphisms in the CYP2C19 gene are known to alter the outcome for patients taking clopidogrel for cardiovascular disease treatment." (PMID 38286794, 2024). "Second, the effect of CYP2C19 polymorphisms on P2Y12 inhibitor efficacy might be less pronounced in the context of SAB than their well-established effects in cardiovascular disease prevention." (PMID 39569238, 2024). "We also found that the mother and daughter are both homozygous for an ultra-rapid metabolism allele at CYP2C19 (Entrez Gene ID 1557), which encodes a key metabolizer of the pro-drug clopidogrel, an antiplatelet agent used in the prevention and therapy of cardiovascular disease." (PMID 21935354, 2011). "Cytochrome P450 2C19 (CYP2C19) closely related to the occurrence and development of cardiovascular diseases." (PMID 41658609, 2026). "For example, individuals with the CYP2C19 poor metabolizer genotype have been shown to have a higher risk of cardiovascular disease, regardless of the antiplatelet clopidogrel bioactivation." (PMID 37111350, 2023). "In addition, miR-6783-3p could target CYP2C19 to regulate clopidogrel resistance in patients with cardiovascular diseases." (PMID 38649946, 2024). "Similarly, it was estimated in a 1000-patient cohort that if all patients had CYP2C19 genotyping, to guide clopidogrel prescribing over a one-year period, 20 deaths due to cardiovascular disease would be averted—a 27% decrease, or one life saved for every 50 patients tested." (PMID 36556194, 2022).
infection (7 papers, 2020 to 2025). The state of being infected such as from the introduction of a foreign agent such as serum, vaccine, antigenic substance or organism. "In conclusion, normal, poor, and intermediate CYP2C19 metabolizers are associated with a higher risk of infections." (PMID 36143168, 2022). "In the multivariate analysis of NM and MR/UM adjusting for age, sex, PPI dose, and comorbidities, CYP2C19 metabolizer status was a significant risk factor for infectious events with higher infection rates in normal metabolizers compared to those with rapid/ultra-rapid metabolizing capacity." (PMID 36143168, 2022). "The group of normal CYP2C19 metabolizers (n = 267; 40%) had a higher infection rate than the MR/MU (n = 220; 33%)." (PMID 36143168, 2022). "Since CYP2C19 inactivates PPIs, genetic variants that increase CYP2C19 function may decrease PPI exposure and infections." (PMID 36143168, 2022). "In our study, baseline infection intensity and not CYP3A4, CYP2C19 and CYP2C9 genotypes was a significant predictor of adverse events following PZQ treatment." (PMID 34531744, 2021).
myopathy (4 papers, 2016 to 2025). A disease of the muscle in which the muscle fibers do not function properly. "Moreover, pharmacogenomic insights exemplified by CYP2C19 genotyping to guide clopidogreland SLCO1B1 testing to mitigate statin-induced myopathy have demonstrated the capacity to reduce adverse events and optimize drug efficacyin routine practice." (PMID 41170027, 2025).
digestive system cancer (3 papers, 2013 to 2023). A primary or metastatic malignant neoplasm involving any part of the digestive system. "The present meta-analysis provides the first comprehensive assessment of the risk of digestive system cancer and CYP2C19 gene polymorphisms." (PMID 23874401, 2013). "In the past decade, the relationship between CYP2C19 polymorphism and digestive system cancer has been reported in various ethnic groups; however, these studies have yielded contradictory results." (PMID 23874401, 2013). "In summary, our meta-analysis suggested that the PM phenotype caused by the variation on CYP2C19 gene is associated with increased risk of digestive system cancer, especially in East Asians." (PMID 23874401, 2013). "Overall, significantly elevated digestive system cancer risk was associated CYP2C19 PM with OR of 1.66 (95%CI: 1.31–2.10, P<10−5) when all studies were pooled into the meta-analysis." (PMID 23874401, 2013). "A total of 18 studies with 4414 digestive system cancer cases and 6628 controls were retrieved based on the search criteria for digestive system cancer susceptibility related to the CYP2C19 polymorphisms." (PMID 23874401, 2013). "Our results demonstrated that the PM genotype of CYP2C19 is a risk factor for developing digestive system cancer." (PMID 23874401, 2013). "In the past decade, the polymorphic effects of two CYP2C19 genotypes/phenotypes, extensive metabolizer and poor metabolizer, on the development of digestive system cancer have been investigated among various populations." (PMID 23874401, 2013). "CYP2C19 belongs to the cytochrome P450 superfamily of enzymes involved in activating and detoxifying many carcinogens and endogenous compounds, which has attracted considerable attention as a candidate gene for digestive system cancer." (PMID 23874401, 2013). "To conclude, our meta-analysis demonstrated an association between CYP2C19 PM genotype and digestive system cancer risk among Asians, but not among Caucasians." (PMID 23874401, 2013). "In the subgroup of ethnicity, we found significant association between CYP2C19 genotype and increased risks of digestive system cancers in Asians but not in Caucasians." (PMID 23874401, 2013). "The results showed that the focus genes for target and digestive system cancers were ACE, PTGS2, CYP2C19, and CYP2A6, while the number of intersections with neurological diseases was 73, and the three shared a focus on ACE, PTGS2 and CYP2C19 (top left)." (PMID 37701374, 2023). "The FCTF model of the local medicinal food Laoxianghuang focuses on the efficacy of digestive system cancers and neurological diseases, with key targets ACE, PTGS2, CYP2C19 and corresponding active components citronellal, trans-nerolidol, linalool, geraniol, α-terpineol, cadinene and α-pinene." (PMID 37701374, 2023).
heart disease (3 papers, 2017 to 2024). "They reported a very high frequency of CYP2C19*2 polymorphism, but this may be due to possible association of this polymorphisms with cardiac diseases." (PMID 34308762, 2021).
infectious disease (2 papers, 2022 to 2025). A disorder directly resulting from the presence and activity of a microbial, viral, or parasitic agent in humans. "For example, CYP2C19 has established EADGIs with 21 medications used in behavioral health, cardiology, gastroenterology, infectious disease, neurology, pain management, and reproductive and sexual health." (PMID 36556194, 2022).
kidney disease (2 papers, 2020 to 2024). "The drug interaction between PPIs and other nephrotoxic drugs metabolized by CYP2C19 could further increase the risk of renal function impairment in patients with renal diseases." (PMID 39716090, 2024). "These metabolites may inhibit cytochrome P450 2C19 (CYP2C19) and cytochrome P450 3A4 (CYP3A4) reversibly, but as recent evidence suggests, they may also be involved in causing kidney disease." (PMID 32566351, 2020).
electrolyte imbalance (1 paper, 2025). "Although increased PPIs exposure in CYP2C19 PMs and IMs is suggested to be the cause of electrolyte imbalance, none of the studies investigated the effect of CYP2C19 variants on the occurrence of ADRs related to PPIs use." (PMID 40070570, 2025).
heart (1 paper, 2016). "Accordingly, CYP2C19 pharmacogenetic profiling may be beneficial for coronary heart patients undergoing PCI to predict the efficacy of treatment with clopidogrel." (PMID 27932982, 2016).
hematologic malignancies (1 paper, 2025). "However, there is limited research on the impact of CYP2C19 gene polymorphisms on VRC concentrations in Chinese patients with hematologic malignancies under different administration routes." (PMID 40746723, 2025). "Therefore, the current study aimed to examine the influence of different administration routes and gene polymorphisms of CYP2C19, CYP3A4 and ABCB1 on the serum VRC concentration among Chinese patients with hematologic malignancies." (PMID 40746723, 2025).
retinopathy (1 paper, 2022). "These analyses showed effects of retinopathy-associated genotypes on increased gene expression for PCSK9 (rs2479409) in skin fibroblasts, for CYP2C19*2 (rs4244285) in skin fibroblasts, liver, and stomach, and for PROX1 (rs340874) in the brain (Consortium, 2015)." (PMID 35600617, 2022).
skin disorder (1 paper, 2018). Any deviation from the normal structure or function of the skin or subcutaneous tissue that is manifested by a characteristic set of symptoms and signs. "Patients with CYP2C19*17/*17 genotype experienced vomiting and skin disorders whereas wild type genotype was connected with swelling (face and peripheral oedema)." (PMID 28685218, 2018).
CYP2C19 also shares sentences with these, for which no sentence is quoted: acute myocardial infarction (4 papers); duodenal ulcer (4); esophagus cancer (4); allergies (3); anxiety disorder (3); asthma (3); gastrointestinal disorders (3); head neck cancer (3); heart failure (3); autoimmune hepatitis (2); biliary tract cancer (2); bladder cancer (2); cerebral infarction (2); essential hypertension (2); hyperglycaemia (2); Hypokalemia (2); ischemia (2); Thrombosis (2); upper respiratory tract infections (2); Adrenal insufficiency (1); alcoholic liver diseases (1); Alzheimer disease (1); androgen excess (1); Apathy (1); aplastic anemia (1); Arthritis (1); asthenia (1); atrophic gastritis (1); Atrophy (1); autism spectrum disorder (1).
A further 82 diseases each share a sentence with CYP2C19 in 1 paper.